AURKA (aurora kinase A)
Diseases named in the same sentence as AURKA in open-access papers (continued):
Sharing a sentence is not in itself a finding about the gene and the disease.
tumor (continued). "Interestingly, among the mutation sites of AURKA in 10,967 tumor samples from 21 types of tumors, the amplification of AURKA was highly associated with mutations of caspases 3, 7, and 8, indicating the biological significance of the caspase 3/7/8-mediated Asp132 cleavage of AURKA in chemotherapy." (PMID 38994036, 2024). "However, ciliogenesis induced by the inhibition of AURKA may cause premature senescence by preventing the formation of the mitotic spindle in non-tumor cells." (PMID 37780208, 2023). "Moreover, AURKA was upregulated in tumour tissues and associated with the BCR of PCa." (PMID 36750558, 2023). "Therefore, we analyzed the correlation between tumor mutation burden and the expression of targets, and the results showed that the expression of AURKA, CCNA2, CCNE1, CDK1, CHEK1, and PLK1 were significantly positively correlated with the tumor mutation burden." (PMID 36483630, 2022). "Hence, AURKA expression is associated with enhanced proliferation of tumor cells." (PMID 32127951, 2020). "However, AURKA is a low-penetrance tumor-susceptibility gene in mice and humans." (PMID 31269749, 2019). "Thus, genomic loss of HMMR/RHAMM may indicate a subset of tumours that are reliant upon AURKA and highly susceptible to AKI." (PMID 23328114, 2013). "When comparing HBV-HCC and Cr-HCC cases with the control group, AURKA immunoreactivity (including both nuclear and cytoplasmic staining patterns) was significantly higher in both tumor groups (p < 0.001)." (PMID 41515655, 2026). "Pharmacologic inhibition of AURKA abrogates squamous features and suppresses tumor growth in patient-derived organoids, xenografts, and orthotopic models, with KMT2D-deficient tumors exhibiting heightened sensitivity." (PMID 41507359, 2026). "Nevertheless, AURKA expression was found to be upregulated in the majority of tumors, suggesting a critical role in tumor development and progression." (PMID 40718709, 2025). "Aurora kinase A (AURKA) is aberrantly expressed in a large number of tumors and promotes tumor progression by regulating the cell cycle, chromosomal instability, and drug resistance." (PMID 40718709, 2025). "We investigated the correlation of AURKA with the tumor immune microenvironment (TIME) to uncover insight into the biological pathways involved in AURKA." (PMID 40718709, 2025). "TIDE analysis showed that OSCC patients had higher TIDE scores when AURKA was highly expressed, suggesting that OSCC tumor cells are prone to immune escape and less likely to benefit from immunotherapy in the presence of high AURKA expression." (PMID 41471272, 2025). "Down-regulation of NKX3.1, a prostate-specific tumor suppressor, mediated by AURKA, is the primary mechanism driving CRPC to differentiate into NEPC." (PMID 40746825, 2025). "In NEPC, over 50% of tumor cells exhibit robust cytoplasmic expression of AURKA, which plays a crucial role in the NED of PCa." (PMID 40746825, 2025). "IHC analysis of tumor tissues revealed that not only AURKA but also p-AKT was suppressed following AS/BJO-NEs treatment." (PMID 41471272, 2025). "For instance, AURKA was consistently associated with poor prognosis, while NLRP6 appeared protective in most tumour types." (PMID 40696496, 2025). "For instance, genes such as AURKA, APEX2, CCNE1, and FOXM1 have been reported to be associated with tumor resistance." (PMID 40098976, 2025). "Less frequent changes, such as AURKA gain, TYK2 activation, and ATRX alterations, are linked to maintenance of the alternative lengthening of telomeres as another mechanism of tumor survival." (PMID 41463204, 2025). "This complexity reflects a further interaction of AURKA subset cell with the tumor microenvironment that is worthy of further investigation." (PMID 40718709, 2025). "Our transcriptome-based analysis of OSCC indicates that AURKA exerts a significant impact on tumor development and patient outcome." (PMID 41471272, 2025).
tumor (continued). "Aurora Kinase-A (AURKA) is a serine/threonine kinase that is highly expressed in various tumor types." (PMID 40718709, 2025). "It was observed that the high-expression group of AURKA exhibited higher tumor purity, whereas the high-expression groups of CYP1A2 and ESR1 were associated with lower tumor purity." (PMID 40864066, 2025). "The potential interaction of AURKA with the AR pathway provided the complexity of tumor progression and drug resistance." (PMID 40718709, 2025). "The AURKA protein is a cell cycle controlled kinase that influences tumor development and progression through its important function in microtubule production and spindle pole stabilization during chromosomal segregation." (PMID 40925573, 2025). "Using the MDA-MB-231 orthotopic mouse model, we treated tumor-bearing mice with vehicle, palbociclib, an AURKA inhibitor (alisertib), or the combination of palbociclib and alisertib." (PMID 39826695, 2025). "The profile of AURKA was heterogeneous, and its function affects or depends on the specific tumor microenvironment (TME)." (PMID 40718709, 2025). "The abnormally high AURKA-expressing subset promoted tumor cell proliferation and migration by regulating cell cycle and mitosis." (PMID 40718709, 2025). "Previous studies have shown that AURKA promotes aberrant proliferation of tumor cells mainly by regulating centrosome maturation and segregation during mitosis, leading to chromosomal instability and cell cycle deregulation." (PMID 40718709, 2025). "Specifically, compared to the NC group, the tumor volume reduction rates were 60% in the sh-AURKA group and 79% in the sh-AURKA+ AS/BJO-NE group." (PMID 41471272, 2025). "Although clinical trials have demonstrated the efficacy of alisertib, a selective inhibitor against AURKA, to decrease tumour growth, alisertib alone has also shown elevated levels of toxicity." (PMID 40107714, 2025). "When AURKA was highly expressed, glycolysis levels were higher in both primary tumor foci and lymph node metastatic foci, and PI3K/AKT pathway activation levels were also higher." (PMID 41471272, 2025). "In our study, we showed that combining an AURKA inhibitor with a targeted radiopharmaceutical markedly decreased tumor growth in vivo compared to either agent alone." (PMID 38869684, 2024). "Silencing AURKA in NB cell lines resulted in diminished proliferation and promoted tumor cell apoptosis." (PMID 39585848, 2024). "Both AURKA inhibition by alisertib and inducible AURKA knockdown potentiated the cytotoxic effects of cisplatin and radiation, leading to tumor regression in doxycycline-inducible xenograft mice." (PMID 39199578, 2024). "Serum AURKA shows promise as a biomarker in various tumours, thus additional studies are warranted to assess its potential clinical utility in HCC." (PMID 38590119, 2024). "Hypoxic conditions are crucial tumour microenvironmental factors that influence AURKA and HIF1A activity in HCC cells." (PMID 38590119, 2024). "Here, they observed that recovery of cilia in the tumor cells by treatment with an Aurora kinase A (AURKA) inhibitor improves response to Hh inhibitors promoting tumor cell death." (PMID 38469231, 2024). "We demonstrate that AURKA can induce the expression of immune checkpoint protein PD-L1, thereby facilitating tumor immune evasion and suppressing the anti-tumor immune response." (PMID 38995006, 2024). "Future studies in this area will enhance our understanding of AURKA’s multifaceted functions in tumor metabolism." (PMID 38521813, 2024). "Tumor-suppressive miRNAs directly target and repress AURKA, while oncogenic lncRNAs and circRNAs enhance AURKA levels primarily by sponging tumor-suppressor miRNAs, thereby driving oncogenic processes." (PMID 39598228, 2024). "The effects of AURKA knockdown and its combination with cisplatin on tumor size were also studied in vivo with xenograft studies." (PMID 39199578, 2024).
tumor (continued). "Overexpression of AURKA has been reported to play a role in various cellular processes that contribute to carcinogenesis and tumor progression." (PMID 39199578, 2024). "The xenograft model of doxycycline-inducible AURKA knockdown NSCLC tumor treated with cisplatin or doxycycline alone demonstrated slower growth of tumor mass compared to that of untreated mice." (PMID 39199578, 2024). "AURKA can have a role in immune cell recruitment and immune microenvironment modulation, which determines the immune response to the tumour, thus possibly influencing prognosis." (PMID 38590119, 2024). "AURKA positivity in the nucleus or cytoplasm was confirmed; its expression in tumor cells was validated as being higher in surrounding cancerous tissues than normal tissues." (PMID 38903715, 2024). "AURKA was highly expressed in patients with multifocal tumor, cervical lymph node metastasis, and an advanced TNM stage, indicating a high probability of recurrence." (PMID 38903715, 2024). "The elevated levels of AURKA hindered the tumor suppressors through phosphorylation, impeded normal functioning, and triggered the activation of oncogenic factors, resulting in chromosomal instability." (PMID 37768502, 2024). "These miRNAs not only modulate AURKA expression but also influence key pathways involved in tumor progression and metastasis." (PMID 39598228, 2024). "Chi-squared analysis revealed that the expression levels of AURKA were closely related to multifocal tumor (P = 0.030), N stage (P = 0.004), TILs (P = 0.014), and BCR (P = 0.010)." (PMID 38903715, 2024). "In this study, silencing AURKA arrested the cell cycle in the G2/M phase in NB tumor cells, as determined via flow cytometry." (PMID 39585848, 2024). "AURKA inhibitors, such as alisertib, inhibit the interaction between N-myc and AURKA to stop tumor growth and progression." (PMID 38903357, 2024). "We found that perturbation of AURKA APA allowed AURKA expression to evade regulation by the tumour suppressor miRNA hsa-let-7a and was sufficient for acquisition of cellular properties associated with oncogenic transformation." (PMID 39527514, 2024). "FBXW7 is considered as a critical tumor suppressor as it degrades many oncoproteins including AURKA." (PMID 39334449, 2024). "When the mice were treated with cisplatin in the setting of AURKA knockdown, an actual reduction in tumor size was observed after day 35 compared to either treatment alone." (PMID 39199578, 2024). "Given AURKA’s critical role in tumor biology, several AURKA inhibitors, such as MLN8237 (Alisertib) and MLN8054, have progressed to the clinical trial stage." (PMID 39834933, 2024). "In a prior study, combination treatment with the AURKA inhibitor alisertib and programmed cell death-ligand 1 (PD-L1) monoclonal antibody showed a synergistic effect in terms of tumor inhibition." (PMID 38903715, 2024). "Recent findings underscore the involvement of the ncRNAs and AURKA axis in tumor development and progression." (PMID 39598228, 2024). "Silencing AURKA inhibited tumor cell proliferation, induced tumor cell apoptosis, and led to cell cycle arrest in the G2/M phase." (PMID 39585848, 2024). "A related study found that AURKA acts as an oncogene to facilitate the promotion of the growth of many tumour types, such as solid tumours and haematologic malignancies." (PMID 38794152, 2024). "High expression levels of AURKA are associated with the progression of HNC and poor prognosis, especially in HPV-negative tumours." (PMID 39518152, 2024). "In order to deeply validate the anti-tumor effect of AURKA inhibitor (TCS7010) in vivo, we established a xenograft model in mice with A673 cells." (PMID 38287009, 2024). "Of 94 NSCLC patient tumor specimens, 91.5% tested positive for AURKA expression, with 34% showing moderate-to-high levels." (PMID 39199578, 2024). "Liu and colleagues noted an increase of AURKA in 24 tumour tissues compared to the matched adjacent tissues." (PMID 38590119, 2024).
tumor (continued). "AURKA expression was predominantly detected in tumor tissues, and approximately 107 patients (78.1%) stained positive; of which, 28, 49, and 30 samples had weak, mild, and strong staining, respectively." (PMID 38903715, 2024). "This research provides valuable insights into expanding the scope of tumor sensitivity to AURKA inhibitors and highlights the need for future studies in diverse tumor types." (PMID 38521813, 2024). "Inhibition of AURKA leads to spindle formation abnormalities and mitotic defects, ultimately resulting in tumor cell death." (PMID 38521813, 2024). "We identified a combination of mitotic inhibitors targeting KIF11 (SB-743921) and AURKA that are effective in inhibiting EWS tumor growth at physiologically relevant nanomolar doses." (PMID 37894278, 2023). "Our analyses further revealed that higher AURKA expression was notably present in younger patients (age ≤ 65) and those in the M1 phase among patients with EAC, providing evidence of AURKA’s potential role in promoting tumor progression." (PMID 37965456, 2023). "When AURKA expression was inhibited, the proliferation and invasion of tumor cells were reduced, and apoptosis was more likely." (PMID 36984548, 2023). "In this context, we previously showed that ASncmtRNA KD induces an increase in miRNAs miR-4485 and miR-1973 and we are currently studying the significance of this effect on the genomic integrity of tumor and normal cells, especially focused on AURKA and TOP2A." (PMID 37888205, 2023). "AURKA (scores 6 and 12) was overexpressed in tumor tissues of 45 (28.13%) GC cases, and the other 115 (71.87%) cases exhibited low expression." (PMID 36937887, 2023). "PKC is a key component in the NK1R-mediated signaling pathway, which has been reported to be responsible for AURKA phosphorylation in tumor and neural cells." (PMID 37385990, 2023). "Numerous malignancies, including GC, are associated with frequent amplification and/or overexpression of AURKA, and its levels are higher in most tumor tissues compared to adjacent normal tissues." (PMID 36937887, 2023). "As an activator and substrate of Aurora kinase A (AURKA), ARPC1B knockout inhibits tumor migration and invasion by downregulating AURKA." (PMID 37795220, 2023). "Among the published reports on the pro-oncogenic effect of AURKA, the promotion of tumor angiogenesis is an important aspect." (PMID 36977984, 2023). "Similar patterns have been seen for WT, where AURKA inhibition impaired tumor growth and induced apoptosis both in vitro and in vivo; however, such effects were improved in RB1-deficient cell lines compared to those with MYC amplification." (PMID 36839989, 2023). "Recent evidence suggests that AURKA inhibition can modulate the tumor microenvironment, enhance T-cell cytotoxicity in vitro, and boost anti-tumor immunity in vivo." (PMID 37965456, 2023). "Concerning the relative mRNA levels, tumor tissue manifested higher AURKA and RBM4-S but lower RBM4-FL than adjacent normal tissue." (PMID 37415951, 2023). "AURKA, a serine/threonine kinase that regulates cell division during mitosis, was overexpressed in several tumor types compared to normal tissues according to TCGA database." (PMID 37608887, 2023). "For example, the small molecule inhibitor MLN8054 has shown promising results in inhibiting AURKA activity and suppressing tumor growth in xenograft models." (PMID 38053725, 2023). "Accordingly, CXCR7 promoted PCa cell proliferation and tumor growth, which was mitigated by AURKA inhibition." (PMID 37347559, 2023). "Further exploration led to the identification and validation of CDK1, CCNB1, AURKA, EZH2, and CCNA2, a five-gene signature with high interactions and potentially associated with tumor stemness, hypoxia enhancement, and TME regulation." (PMID 37189841, 2023). "AURKA also regulates organization of microtubules required for cellular migration and also enhances migration of tumor cells through several pathways." (PMID 37384380, 2023).
tumor (continued). "These events are sensitive to down-regulation of their upstream mechanisms: a combination of Aurora kinase A and histone deacetylase inhibitors suppressed the tumor." (PMID 37297004, 2023). "In this study, we employed a synergistic combination of mitotic inhibitors targeting KIF11 and AURKA to halt EWS tumor growth in vitro and in vivo, as assessed in a mouse xenograft model." (PMID 37894278, 2023). "Alisertib is a small molecule inhibitor of Aurora kinase A that disrupts the N‐myc‐Aurora A protein complex, thus inhibiting the mitotic process and tumour growth." (PMID 37025467, 2023). "N-Myc overexpression is common in NEPC and destabilization of N-Myc by AURKA inhibition reduces tumor burden." (PMID 37385990, 2023). "AURKA is involved in the regulation of multiple signalling pathways, enabling tumour cells to escape apoptosis and proliferate massively." (PMID 36471438, 2022). "In a large cohort of NSCLC patients (n = 362) AURKA was highly overexpressed in the tumor tissues compared to corresponding normal lung tissue." (PMID 36387232, 2022). "Altogether, these results demonstrate that RBM4-S plays an opposite role as compared to the canonical tumor suppressor RBM4-FL, therefore, the splicing switch towards RBM4-S is partially responsible for AURKA-regulated tumor growth." (PMID 35361747, 2022). "The function of AURKA substrates, some of which are mitotic regulators, tumor suppressors, or carcinogenes, is modulated by AURKA-mediated phosphorylation." (PMID 35574421, 2022). "The use of alisertib for AURKA inhibition in the EAC xenograft model led to a decrease in IRE1α phosphorylation with a significant reduction in tumor growth." (PMID 35326553, 2022). "After selecting AURKA as the target gene, we compared the expression of AURKA between tumor samples and normal samples in the GSE12452 and GSE13597 datasets." (PMID 36072667, 2022). "PARADIGM pathway features corresponding to the mitotic genes TPX2, RAE1, UBE2C, AURKA show increased activity in tumours with high NCS, consistent with the known role of chromosome segregation errors in W-CIN." (PMID 35326573, 2022). "AURKA has also been identified to affect tumor immunological patterns in diverse malignancies by controlling the expression of particular immune checkpoint genes, according to subsequent research." (PMID 36685952, 2022). "Oxethazaine, as a FDA-aproved drug, has already proved itself in clinical trials, therefore, it has good potential for tumor therapy as a new AURKA kinase inhibitor with low toxicity." (PMID 35217647, 2022). "The results showed significantly greater expression of AURKA in tumor tissues compared with normal tissues (p < 0.05)." (PMID 36072667, 2022). "As a proof of concept of this problem, some companies are developing AURKA inhibitors in nano-formulations with the aim to augment the therapeutic index by a selective delivery of the compound in the tumor." (PMID 35249548, 2022). "Supporting these data, inhibition of the AURKA/STAT3 signaling pathway promoted effective T-cell infiltration into the tumor microenvironment and improved anti-PD-1 efficacy." (PMID 35267462, 2022). "AURKA immunoreactivity was scored as positive due to the presence of nuclear and cytoplasmic immunoreactivity in the tumor cells." (PMID 35967099, 2022). "In HCC, overexpression of AURKA and AURKB is associated with tumor aggressiveness, an unfavorable prognosis, and poorer outcomes, and their co-expression is an independent predictor of PFS and OS." (PMID 35062934, 2022). "Alisertib, a specific Aurora kinase A antagonist has already been found to induce a potent reduction in tumor growth in solid as well as hematologic neoplasms." (PMID 36269546, 2022). "The results showed that AURKA transcript expression in tumor tissues was significantly higher compared to normal tissues." (PMID 35217647, 2022). "In recent years, increasing evidence has demonstrated a potential relationship between AURKA expression and tumor immunity." (PMID 35845594, 2022).